IL4 (interleukin 4)
Diseases named in the same sentence as IL4 in open-access papers (continued):
Sharing a sentence is not in itself a finding about the gene and the disease.
infection (continued). "Here, we performed time course kinetics experiments on bone marrow-derived macrophages (BMDMs) and human monocyte-derived macrophages (MDMs) alternatively activated with IL-4, IL-13, or a combination of IL-4/IL-13, followed by infection with Mtb clinical Beijing strain HN878." (PMID 30941122, 2019). "Interestingly, a prominent peak pattern of IL-4 and IL-5 was noted in cerebra of T. canis-infected mice in the acute and subacute phase of infection." (PMID 31315623, 2019). "Finally, it has also been reported that STAT1 regulates the secretion of IL-4 by basophils upon infection with hRSV." (PMID 30936869, 2019). "The initial rise in IL-4 levels might be due to a Th2 response, but the increased levels observed at later times of infection indicate a contribution from Th3 T-reg cells." (PMID 31548315, 2019). "IL-12 also suppresses IL-4 production which is capable of resolution of the infection." (PMID 30642262, 2019). "Flow cytometry and single-cell RNA-seq analysis revealed that around 70% of the IL-4-producing cells are NKT cells, whereas the remaining ones are mainly T cells, excluding a significant contribution by ILC2s and TfH cells to the IL-4 production at early stages of infection." (PMID 29249358, 2018). "However, despite significant IFN-γ reduction in cardiac tissue, TNF-α expression was similar between WT and IL-4−/−, both in uninfected mice (NI WT vs. NI IL-4−/−, p > 0.17) and after infection (Inf WT vs. Inf IL-4−/−, p > 0.5)." (PMID 30622430, 2018). "The initial data on the adaptive immune response in different mouse strains infected with L. major have shown that the susceptibility or resistance to this infection is related to the production of certain cytokines of the Th1 or Th2 profile, respectively, IFN-γ, or IL-4 and IL-13." (PMID 30150896, 2018). "Because of the central role of NKT cells in producing IL-4 early after infection, we wondered whether CD1d−/− mice would have reduced numbers of IL-4-secreting cells." (PMID 29249358, 2018). "Based on the results obtained for the different sampling points in both trials, up-regulation of il4/13a may appear slightly more consistent and specific to the infection than il4/13b2." (PMID 30209326, 2018). "Therefore, IL-4/IL-13 responsive B cells are important for maintaining optimal cellular immunity during infection with S. mansoni." (PMID 30619289, 2018). "In resistant mice, treatment with rIL-4 at the beginning of the infection did not induce the susceptible profile due to the noncontinuous production of IL-4 during the infection." (PMID 30150896, 2018). "Expression levels of Tnf-α, Ifn-γ and Il-12, Il-4 and Tgf-β were significantly upregulated after infection, a cytokine milieu supportive of immunopathogenesis, which may damage the hepatobiliary tract." (PMID 29953446, 2018). "However, in IL-4 absence, IFN-γ expression was significantly reduced, either basal (NI WT vs. NI IL-4−/−, p = 0.009, t = 3.315) or after infection with Colombian strain (Inf WT vs. Inf IL-4−/−, p = 0.001, t = 4.43)." (PMID 30622430, 2018). "Furthermore, when CD4+ T cell type 2 responses were measured in the lungs at day 10 post-infection, Retnla +/- mice exhibited significantly increased numbers of IL-4+ and IL-13+ CD4+ T cells." (PMID 30500858, 2018). "Interestingly, although the levels of serum IL-4 were significantly reduced in infected mb1creIL-4Rα−/lox mice at 16 weeks post-infection, the levels of IL-4 were almost 3-fold higher in mice lacking IL-4Rα expressing B cells at 24 weeks post-infection." (PMID 30619289, 2018). "However, this previously unreported NKT cell-mediated wave of IL-4 production occurs at the early stages of infection, even before the appearance of TfH cells or germinal centers." (PMID 29249358, 2018). "Thus, the balance of monocytic vs. resident M(IL-4) numbers varies between inbred mouse strains and impacts infection outcome." (PMID 29299998, 2018).
infection (continued). "While the general understanding is that IL-4 induces a Th2 response detrimental to CL, there have been studies demonstrating that the early production of IL-4 at the site of infection in BALB/c mice drives a beneficial Th1 response under the instruction of dendritic cells (DCs)." (PMID 30275010, 2018). "Indeed, NKT cells secrete an early wave of IL-4 and constitute up to 70% of the total IL-4-producing cells during the initial stages of infection." (PMID 29249358, 2018). "Furthermore, in IL-4 absence, significantly higher IL-10 levels were observed in cardiac tissue following infection (Inf WT vs. Inf IL-4−/−, p = 0.004, t = 3.42)." (PMID 30622430, 2018). "Mice of a C57BL/6 background (B6.WT) display a localized, self-healing infection characterized by interferon-γ (IFN-γ) production, while mice of the BALB/c background respond to infection with a preferential production of Th2 cytokines, such as IL-4, IL-10, and IL-13." (PMID 29403488, 2018). "Indeed, infection with L. major IL-81 promastigotes has been shown to induce keratinocytes to rapidly secrete IL-12, IL-1β, and IL-4 in C57BL/6 mice." (PMID 30275010, 2018). "Thus, this study is aimed at evaluating IL-4 influence on acute phase of Trypanosoma cruzi experimental infection through dosage of cytokine levels in cardiac homogenate of infected Balb/c WT and Balb/c IL-4−/− as well as its histopathological repercussions." (PMID 30622430, 2018). "To assess the contribution of NKT and TfH cells to the pool of IL-4-producing cells at different times of infection, we gated on TCRβ+ IL-4-GFP+ lymph node cells and analyzed the proportion of this population that was CD1d-tetamer+ (NKT cells) or CXCR5+ (TfH cells)." (PMID 29249358, 2018). "Alternatively, their production might have been inhibited by IL-4 and IL-10 which were both increasingly expressed after infection." (PMID 29973271, 2018). "Therefore, in response to infections, females usually activate Th2 responses and produce high levels of interleukins (IL) IL-4, IL-5, and IL-10." (PMID 29925409, 2018). "IL-13 and IL-4 have emerged as key mediators of inflammation–and infection–driven fibrosis." (PMID 29782549, 2018). "Interestingly, a recent report showed that TfH cells only switch to IL-4 production at the late stages of the infection process." (PMID 29249358, 2018). "Higher levels of IL-4 production in the young mice at acute phase could lead to significant stimulation of B cells and antibody production later in infection that is critical for B. burgdorferi clearance." (PMID 30619263, 2018). "At 48 h after infection, the results were similar for both IL-4 and IL-10." (PMID 28767981, 2017). "Indeed, in a human patient with vascular pythiosis, high levels of IL-4 and IL-5 cytokines have been detected during infection." (PMID 28542438, 2017). "Interestingly, however, IL-4Rα knockdown did not prevent the recall of a strong type 2 response as judged by IL-4 levels and the considerable reduction of the number of remnant worms in the gut of IL-4Rα knockdown mice during secondary infections." (PMID 28651009, 2017). "Furthermore, Foxp3YFP+ cells isolated from H. polygyrus–infected mice (HpTR) had reduced levels of pSTAT6 ex vivo, further highlighting a role for IL-4 signaling in T reg cells during infection." (PMID 28507062, 2017). "Since viral capture is around three-fold higher in LPS-matured DCs and six-fold higher in IFN-α DCs than in IL-4 DCs, we hypothesized that trans-infection might occur preferentially with mature DCs compared to IL-4 DCs." (PMID 28426803, 2017). "However, while a single infection of S. japonicum resulted in increased level of IL-4, a decrease in IL-4 was observed in mice of the CI group." (PMID 28465515, 2017). "For il-4, this increase was only statistically significant at 24 h post-infection (p = 0.02)." (PMID 28771523, 2017).
infection (continued). "Likewise, infections can endure when Tregs are unable to migrate into the periodontium and modulate the infection due to critical modulators such as IL-4, CCL2, and CCR4." (PMID 29163477, 2017). "V3000 infection uniquely modulated several inflammatory signaling pathways such as IL-2, IL-4, IL-8, IL-9, IL-12 and IL-17A along with the unfolded protein response, gap junction signaling, crosstalk between DCs and NKCs, interferon and JAK/Stat signaling pathways." (PMID 28446152, 2017). "IL-4 and IL-6 were undetectable, but high cytokine levels were detected ≥10 days after infection." (PMID 29312230, 2017). "We have previously shown that productive infection of IL-4 DCs was the main route of HTLV-1 transmission to lymphocytes, although passive transfer from HTLV-1-exposed IL-4 DCs in presence of AZT may have occurred in rare cases." (PMID 28426803, 2017). "Moreover, in the same study, the upregulation of IL-4 mRNA observed in C57BL/6 keratinocytes was shown to be restricted to a very small time window at the onset of infection." (PMID 29067025, 2017). "Previous studies have demonstrated the production of interferon-gamma (IFN-γ), interleukin 12 (IL-12), nitric oxide (NO) and tumour necrosis factor alpha (TNF-α) in early stages of infection and later interleukin 13 (IL-13), interleukin 4 (IL-4) and interleukin 10 (IL-10)." (PMID 28655350, 2017). "Interestingly we found that the levels of TNF-α, IL-2 and IL-4 returned to baseline or were decreased compared to the uninfected control group by 4 to 6 days post-infection." (PMID 28114957, 2017). "However, in contrast to IL-4−/− mice, IL-4Rα−/− mice developed progressive disease and necrotic footpad lesions during the chronic phase of infection." (PMID 29176972, 2017). "Interestingly, while CD4+ T cells from both groups proliferated based on CFSE-staining, the Th2 cytokine IL-4 was reduced in co-infected animals compared to helminth single infection." (PMID 28791259, 2017). "A CSF pro-inflammatory response consists of an interplay of Th1 (IFN-γ and IL‐6), Th2 (IL‐4 and IL‐10) and Th17 cytokines (IL‐17A) and has been shown to be highly predictive of increased macrophage activation, rapid clearance of infection and consequently better survival in patients with CM." (PMID 28486489, 2017). "Furthermore, in the early phase of infection, the level of IL-4 can block the Th1 cell conversion and IFN-γ produce." (PMID 28936207, 2017). "In infection, IL-4 levels significantly increased over course of time." (PMID 29348965, 2017). "Taken together, these results demonstrate that during the first hours of infection, il-4 gene expression can be detected at the infection site selectively in mast cell, but il-4 mRNA expression was not modulated during L. major infection (analyzed at 0, 4,12,16, and 24 h p.i.)." (PMID 29067025, 2017). "Importantly, stimulation of harvested MLN cells with 20μg/ml α-CD3 revealed that production of Th2 cytokines (IL-4, IL-5, IL-13 and IL- 10) peaked from day 6 to day 7 post-infection and diminished at day 9 and 12 post-infection." (PMID 28651009, 2017). "However, Th1 markers expression was preceded (at 14 days post-infection) by expression of the master regulator transcription factor for Th2 cells, GATA3, and the associated Th2 cytokine, IL-4." (PMID 28103263, 2017). "Moreover, LA-ET enhanced interferon-γ and interleukin-4 and -10 production, which was associated with mixed helper T (Th1/Th2) cell responses, and protected against EHEC O157:H7 colonization and infection in mice at a rate of 80%." (PMID 28360900, 2017). "infection via IL-4-induced differentiation of naive CD4+ T cells into TH2 cells." (PMID 29295550, 2017). "Furthermore, deletion of the α chain of the IL-4 receptor on DCs turn BALB/c hypersusceptible to infection with L. major, indicating a protective role of IL-4 during Leishmania infection." (PMID 28567039, 2017).
infection (continued). "Besides the full protein, additional A3Z1 truncated protein forms lacking the cytidine deaminase motif (A3Z1Tr) were detected following immune stimulation with IFN-γ, interleukin 4 (IL-4) or infection with SRLVs." (PMID 29149056, 2017). "Gfi1-deficient T cells failed to optimally produce IL-4 after in vitro stimulation or following infection with the helminth parasite Schistosoma mansoni." (PMID 28443098, 2017). "Our previous finding that pathologic parasite-induced arginase is amplified by IL-4 in experimental VL suggests that IL-4-producing CD4+ T cells may contribute to impaired control of infection." (PMID 28103263, 2017). "Mast cells appeared to be the major dermal cells expressing IL-4 early after infection, suggesting that this source of IL-4 could play a role locally." (PMID 29067025, 2017). "Moreover, M(LPS + IFN-γ) cells had reduced production of TNF-α after infection but were still producing significantly higher amounts than M0 and M(IL-4)." (PMID 29250063, 2017). "During pre-feeding phase, the impact of these diets on gill, the major route of infection, was examined by RNA-seq showing the changes in the mannose receptor and genes related to IL4 signalling, which may modify the host response to the infection." (PMID 28254621, 2017). "An increase of Il4, Arg1 and Ifng mRNAs in the spleen was observed in the R12 group, suggesting the existence of peripheral systemic mixed Th1/Th2 active immune responses in secondary infection." (PMID 28362822, 2017). "Protection was associated with increased pulmonary type 2 cytokines IL-4 and IL-13 but not IL-33 at day 5 post infection." (PMID 26900854, 2016). "In addition, IL-4/13A has been found to be up-regulated in rainbow trout Oncorhynchus mykiss epidermis 9 days post-infection with Ichthyobodo necator compared with uninfected fish." (PMID 26870894, 2016). "We compared the expression profile of Th1 (IFNγ) and Th2-associated (IL-4 and IL-10) mRNAs in dLNs of WT and CatB-/- mice during infection since we found no detectable transcripts in the FPs." (PMID 27182703, 2016). "At the beginning of infection (first 4 weeks), parasite replication is associated with the immune cell inability to produce IFNγ and IL2 (macrophage-activating cytokines), whereas production of IL4 or IL5 is conserved." (PMID 26969511, 2016). "The IL-4 and IL-13 receptor subunits are expressed at low levels under normal homeostatic conditions, but are influenced by hormones, cellular/oxidative stress, infection and inflammation." (PMID 26870894, 2016). "Infection with helminths has a profound effect on the immune system resulting in polarization towards Th2, characterized by high levels of cytokines such as interleukin-4 (IL-4), IL-5, IL-13 and high serum levels of immunoglobulin E." (PMID 26852392, 2016). "IFN-g, IL-4, and IL-10 production in adult descendants ofschistosomotic mothers after postnatal infection - Splenocytes from animalsof the groups studied were cultured in the presence of OA or Con-A and the supernatantswere collected to measure the secreted cytokines." (PMID 26872339, 2016). "IL-4 levels were measured at all the time points but it could be detected only at 60 days post infection." (PMID 27148868, 2016). "Gp91phox−/− footpads expressed higher mRNA levels for IL-4, which could indicate an anti-inflammatory status at later times of infection." (PMID 27056545, 2016). "Immunosuppressive cytokines, notably IL-4, are involved in the exacerbation of infection." (PMID 27257862, 2016). "However, perhaps if the infection is under control, the pathogen is unable to evade immunity in vaccinated fish with the expression of IL-4/13 paralogues being maintained." (PMID 26870894, 2016). "The intracardiac route is responsible for the development of Th2 immune response that is characterized by IL4 production and increased levels of IgG1 and is associated with IL10 production by Treg cells, thus allowing the establishment of a persistent infection." (PMID 26969511, 2016).
infection (continued). "Additionally, IL-4 has been found to enable productive infection of CD38+ T cells by X4-tropic HIV-1." (PMID 27064238, 2016). "However, basophils are redundant for TH2 differentiation following infection with the natural helminth parasite of mice Heligmosomoides polygyrus, indicating that other sources of IL-4 are required." (PMID 26883724, 2016). "There is a relationship between the Th2 profile response to SEA, many authors have demonstrated that an average of 6–8 weeks after infection by S. mansoni an increase on the expression of IL-5 and IL-4 occurs in the serum in response to the presence of eggs in the portal circulation." (PMID 27378927, 2016). "In contrast, IL-4 primed (M2) macrophages while initially containing fewer internalised P. gingivalis than IFN-γ primed cells at 1 hour were unable to completely clear the infection by 24 hours." (PMID 27383471, 2016). "During cutaneous Leishmania mexicana infection, for example, researchers observed a slight reduction in IFN-γ and IL-4 production in Icos−/− mice at week 6 post-infection, while the production of both cytokines was substantially reduced in ICOS-deficient mice by week 12 post-infection." (PMID 27559335, 2016). "Moreover, more severe skin lesions in BALB/c than in C57BL/6 mice correlate with higher IL-4 levels observed in BALB/c mice, according to models of P. brasiliensis infection in which elevated levels of IL-4 are related to a worsening of the infection." (PMID 27051673, 2016). "Finally, primary infections of rats or mice with the rodent parasites, S. ratti and S. venezuelensis respectively, results in a Th2 response, with production of IL-4, IL-5 and IL-13 and concomitant suppression of IFNγ." (PMID 26730582, 2016). "Interestingly, the expression of IL-4/13B1 was higher in vaccinated fish than in naïve fish during the early infection phase (24 h and 48 h) in both gills and HK." (PMID 26870894, 2016). "This well established chain of immunological events in the resistant C57BL/6 mouse contrasts with the immune response to L. major in the genetically susceptible (i.e., non-healing) BALB/c mouse which shows an early and sustained IL-4 expression that results in a progressive infection." (PMID 26834705, 2015). "CD4 cells, also known as helper T- cells (Th1/Th2) help fight infection by producing cytokines such as IFN-g (Th1) that generally promote cell-mediated immunity or IL-4 (Th2) which fights infection by triggering humoral immune responses through antibody production." (PMID 26371878, 2015). "IL-4 alleviated the impairment of the mitochondrial phosphorylation caused by the cytokines and infection, together or alone, to a degree similar to non-treated mucosal membranes." (PMID 26481427, 2015). "Thus, as the concentration of IFNγ and TNFα increase during the latter time points of infection and clearance in WT mice, the concomitant increase of IL-4 and IL-6 appears to protect the mitochondrial functions of the colonic epithelium." (PMID 26481427, 2015). "Splenocytes removed from infected animals and stimulated in vitro with a total parasite extract (FhTE) produced high levels of IL-4, IL-5 and IL-10, with significant higher levels of IL-4 and IL-10 as soon as the first wpi, reaching a plateau at week 2 after infection." (PMID 26720149, 2015). "However, in contrast to the recruitment of Th17/Th1 cells at 3 days post-infection, Th2 cells and the prototypical cytokine IL-4 were significantly increased at 5 days after inoculation in the present study." (PMID 26230498, 2015). "The high expression of IL-4 in T. crassiceps + DSS mice suggests that this infection may maintain the numbers of goblet cells." (PMID 26090422, 2015). "Thus, larval growth requires only that eosinophils be derived from IL-4 competent donors and the mechanism does involve amplification of IL-4 production by other cells during infection." (PMID 26720604, 2015).